GGCT (gamma-glutamylcyclotransferase)
Description:
Catalyzes the formation of 5-oxoproline from gamma-glutamyl dipeptides and may play a significant role in glutathione homeostasis. Induces release of cytochrome c from mitochondria with resultant induction of apoptosis.
Synonyms: C7orf24; CRF21; MGC3077; Ggc; GCTG
Tractability: Small molecule: it has a high-quality binding pocket. PROTAC: ubiquitination databases record sites on it; its protein half-life has been measured.
Target class: Enzyme; Lyase
Gene: Protein-coding gene on chromosome 7 (30,496,620 to 30,504,850, reverse strand). Ensembl gene ENSG00000006625.
Pathways (Reactome):
Metabolism: Glutathione synthesis and recycling
Gene Ontology:
Molecular function: gamma-glutamylcyclotransferase activity; protein homodimerization activity
Biological process: release of cytochrome c from mitochondria
Cellular component: cytosol; extracellular exosome
Genetic constraint (gnomAD): Loss-of-function variants: 14 observed, 16.39 expected, observed/expected ratio (o/e) 0.85, 90% interval 0.56 to 1.34. The upper end of that interval is the gene's LOEUF score, 1.34, which puts it in group 5 of 6, group 1 being the genes least tolerant of losing a copy. Missense variants: 143 observed, 165.65 expected, observed/expected ratio (o/e) 0.86, 90% interval 0.75 to 0.99. Synonymous variants: 51 observed, 60.56 expected, observed/expected ratio (o/e) 0.84, 90% interval 0.67 to 1.06.
Homologues: Orthologues: chimpanzee GGCT (100% identical), macaque GGCT (98% identical), dog GGCT (86% identical), pig GGCT (86% identical), rabbit GGCT (84% identical), guinea pig GGCT (83% identical), rat Ggct (83% identical), mouse Ggct (82% identical), zebrafish ggctb (56% identical), tropical clawed frog ggct (48% identical), Caenorhabditis elegans C44B7.7 (38% identical), Drosophila melanogaster CG32196 (36% identical), and 1 more.
Diseases named in the same sentence as GGCT in open-access papers:
GGCT is named in the same sentence as 41 diseases in open-access papers, as found by Europe PMC text mining. Sharing a sentence is not in itself a finding about the gene and the disease. The quoted sentences say what the papers report.
breast carcinoma (7 papers, 2015 to 2025). "Down regulation of GGCT activity has previously been implicated in drug resistance in an adriamycin-resistant breast cancer cell line MCF-7 (MFC-7/ADR)." (PMID 29209592, 2017). "Anti-GGCT siRNA has been demonstrated as a promising strategy for treating resistant MCF-7 breast cancer." (PMID 39309810, 2024). "It has already been reported that GGCT protein or mRNA expression is up-regulated in various cancers, including bladder urothelial carcinoma, breast cancer, and osteosarcoma." (PMID 31400748, 2019). "Recently, it has been reported that the downregulation of GGCT elicits an anti-proliferative effect in some cancer cell lines, such as breast cancer cell lines MCF-7, MCF-7/ADR, and MDA-MB-231." (PMID 31878259, 2019). "Knockdown of GGCT in MCF7 breast cancer cells significantly upregulated p21WAF1/CIP1, and the induction of cellular senescence and subsequent growth inhibition induced by GGCT depletion was dependent on p21WAF1/CIP1 upregulation." (PMID 27658708, 2016). "In contrast, in GGCT silenced MDA-MB-231 breast cancer cells, GGCT depletion upregulated p16INK4A, which played a regulatory role in senescence induction, instead of p21WAF1/CIP1." (PMID 27658708, 2016). "GGCT silencing caused cellular senescence not only in MCF7 and MDA-MB-231 breast cancer cells, but also in other cancer cells, as detected by SA-β-Gal positivity." (PMID 27658708, 2016). "In addition, they also studied the expression of GGCT in cancers other than breast cancer and reported that high expression of GGCT was observed in 58% of uterine cervical cancers, 38% of lung cancers, and 72% of colon cancers." (PMID 26339607, 2015). "GGCT depletion induced the expression of p16INK4A, which regulated senescence induction in GGCT-silenced MDA-MB-231 breast cancer cells." (PMID 27658708, 2016). "In previous in vitro studies, forced expression of GGCT in NIH3T3 cells (mouse fibroblasts cells) increased the rate of cell proliferation, and conversely, knockdown of GGCT significantly inhibited the growth of various cancer cells including lung, prostate, bladder, and breast cancer cells." (PMID 27658708, 2016).
lung carcinoma (4 papers, 2015 to 2025). "GGCT−/− mouse show normal development; however, GGCT deficiency inhibits cancer cell proliferation and primary cell transformation and reduces lung cancer formation in Kras G12D mouse model." (PMID 31400748, 2019). "We identified GGCT as a target of oncogenic Ras and that it is required for oncogenic Ras-induced primary mouse cell proliferation and transformation and in vivo lung cancer formation in the LSL-Kras G12D mouse model." (PMID 31400748, 2019). "More importantly, using a LSL-Kras G12D lung cancer mouse model, we demonstrated a critical role of GGCT in oncogenic Ras-induced in vivo tumorigenesis." (PMID 31400748, 2019). "In previous studies, it wasindicatedthat knockdown of GGCT weakened proliferation and colony formation abilities of lung cancer cells through G0/G1 phase arrest." (PMID 27905872, 2016). "GGCT chromosome locus 7p14.3 was reported to be amplified in lung cancer, and in the 7p14.3 region, GGCT is the top significantly expressed up-regulated gene, suggesting that GGCT could also be the target of 7p14.3 amplification in lung cancer." (PMID 31400748, 2019). "In addition, GGCT mRNA expression also significantly correlates with GGCT protein level in lung cancer cell lines." (PMID 31400748, 2019). "To further investigate the in vivo function of GGCT in oncogenic Ras-induced cancer formation, we crossed GGCT−/− mouse with (Lox-Stop-Lox) LSL- Kras G12D mouse model and induced lung cancer formation through intranasal inhalation of Cre recombinase-expressing adenovirus." (PMID 31400748, 2019). "Furthermore, results of cell cycle and apoptosis analysis revealed that GGCT inhibition negatively regulated gastric cancer progression via induction of cell arrest and late apoptosis in MGC80-3 cells, in consistent withthe study of GGCT in lung cancer." (PMID 27905872, 2016). "With newly generated GGCT knockout mouse model and primary cells, we demonstrated a critical role of GGCT in GSH homeostasis and redox balance, critical for primary cell transformation and lung cancer formation, but not normal mouse development." (PMID 31400748, 2019).
bladder cancer (3 papers, 2016 to 2025). "Knockdown of GGCT can suppress cell proliferation ability in bladder cancer cells and induced the cell cytotoxicity against MCF-7/ADR cells in vitro and in vivo." (PMID 27905872, 2016).
colorectal cancer (3 papers, 2018 to 2022). A primary or metastatic malignant neoplasm that affects the colon or rectum. "For example, when GGCT was silenced in cultured colorectal cancer cells, it was sufficient to trigger caspase-3-mediated apoptosis." (PMID 29867309, 2018). "Moreover, GGCT depletion inhibited the growth of cancer cell lines in vitro, including osteosarcoma, colorectal cancer and ovarian cancer cells." (PMID 35329989, 2022).
gastric cancer (2 papers, 2016 to 2024). A primary or metastatic malignant neoplasm involving the stomach. "However, the underling mechanism of how GGCT regulates gastric cancer remains elusive." (PMID 27905872, 2016). "The co-expression of glutaminase 1 (GLS1) and gamma-glutamylcyclotransferase (GGCT), constituents of glutamine metabolism, was strongly associated with histological grade, lymph node metastasis, and TNM stage III/IV of gastric cancer." (PMID 38962317, 2024). "More importantly, cell apoptosis analysis further revealed that GGCT inhibition induced early and late cell apoptosis in gastric cancer." (PMID 27905872, 2016). "Colony formation assay revealed that depletion of GGCT reduced the colony formation ability in gastric cancer cells." (PMID 27905872, 2016). "Knockdown of GGCT weakened cell proliferation and colony formation abilities of gastric cancer cells via increasing cell cycle arrest and inducting late apoptosis." (PMID 27905872, 2016). "Results of searches in Oncomine database revealed that expression of GGCT was significantly increased in human gastric cancer as compared with healthy gastric tissues as shown in Wang (p = 0.001) and Cui datasets (p = 0.008)." (PMID 27905872, 2016). "Knockdown of GGCT with the shRNA system significantly suppressed cell features, including cell proliferation, colony formation ability in gastric cancer cells." (PMID 27905872, 2016). "Then a series of functional assays, including MTT, colony formation and flow cytometry analysis were conducted on gastric cancer cells following GGCT knockdown." (PMID 27905872, 2016). "Taken together, GGCT was overexpressed in many cancer cells, including gastric cancer." (PMID 27905872, 2016). "This study suggests GGCT is essential for gastric cancer proliferation and its downregulation may provide a potential anticancer therapy for gastric cancer." (PMID 27905872, 2016). "As GGCT has been reported to be upregulated in several cancers, we conducted a review of previous microarray data for the expression of GGCT on mRNA level in human gastric cancers." (PMID 27905872, 2016). "Gamma glutamylcyclotransferase (GGCT) has been proved to be involved in various cancers, but the biological function of GGCT in gastric cancer is still largely unknown." (PMID 27905872, 2016). "Here, we observed that GGCT depletion could remarkably inhibit cell proliferation and colony formation activities ofhuman gastric cancer cells." (PMID 27905872, 2016). "Furthermore, we found that depletion of GGCT promotes late apoptosis and induced gastric cancer cells to be arrested in sub-G1 and G2/M phases." (PMID 27905872, 2016). "We found GGCT is commonly up-regulated in gastric cancer tissues." (PMID 27905872, 2016). "However, what is the potential correlation between the dysregulated cycle of glutathione and cell division, and whether downregulation of GGCT interferes with the transportation of amino acids leading to cell division disruption in gastric cancer need further investigation." (PMID 27905872, 2016).
prostate carcinoma (2 papers, 2015 to 2016). A carcinoma that arises from epithelial cells of the prostate gland. "Recently, we found the inhibitory efficacy of the combined use of docetaxel, a standard chemotherapeutic agent for prostate cancer, with anti-GGCT siRNA using prostate cancer cell lines." (PMID 26339607, 2015). "Knockdown of GGCT induced cellular senescence, as detected by SA-β-Gal staining, in MCF7 and MDA-MB-231 cells, as well as other cancer cell lines, including PC3 and LNCaP prostate cancer cells, HeLa cervical cancer cells, and A172 glioblastoma cells." (PMID 27658708, 2016).
bladder urothelial carcinoma (1 paper, 2019). "GGCT was previously named C7orf24 and was originally identified as a protein up-regulated in bladder urothelial carcinoma." (PMID 31400748, 2019).
coronary artery disease (1 paper, 2025). "In addition, GGCT may also be involved in the regulation of glutamate metabolism–related pathways, which are associated with the interconnection between T2D and coronary artery disease (CAD)." (PMID 41306918, 2025).
diabetes (1 paper, 2025). "It has been reported that increased plasma levels of APEX1, CD55, PSME2, and SERPINC1 are significantly associated with hypertension, and increased plasma levels of APEX1, CD55, GGCT, KRT17, PSME2, and SERPINC1 are associated with diabetes." (PMID 41156831, 2025).
endometrial cancer (1 paper, 2024). Primary or metastatic malignant neoplasm involving the endometrium (mucous membrane that lines the endometrial cavity). "A 5-biomarker panel of cervico-vaginal fluid proteins combining APOE, GGCT, CFAB, LY6D and CEAM5 predicted advanced stage endometrial cancer with AUC 0.96 (0.92–1.00)." (PMID 38513301, 2024).
endotoxemia (1 paper, 2025). "APIP and GGCT were identified in the perfused heart dataset and found to be thiol redox modulated in hearts from mice subjected to endotoxemia or the STZ Type I diabetes model." (PMID 40319072, 2025).
ischemic stroke (1 paper, 2022). A stroke disorder caused by obstruction of blood flow to the brain, due to thrombotic (local blood clot formation) or embolic (due to a blood clot or other material traveling from another site) event. "The present and previous studies clearly show that polymorphisms of key genes involved in glutathione biosynthesis such as GCLC, GCLM, GSS (glutathione synthase), and GGCT (gamma-glutamylcyclotransferase) are important contributors to the pathogenesis of ischemic stroke." (PMID 35455093, 2022).
urothelial carcinoma (1 paper, 2015). A malignant neoplasm derived from the transitional epithelium of the urinary tract (urinary bladder, ureter, urethra, or renal pelvis). "We also reported a high expression of GGCT in various human cancer cell lines other than urothelial carcinoma." (PMID 26339607, 2015).
cancer (17 papers, 2015 to 2025). A tumor composed of atypical neoplastic, often pleomorphic cells that invade other tissues. "Their report strongly suggested that high expression of GGCT in cancer cells is caused by a structural change in the chromatin of the GGCT gene associated with the oncogenic transformation of the cells." (PMID 26339607, 2015). "Therefore, the high expression of GGCT in cancer cells is caused by a structural change in the chromatin of the GGCT gene associated with the oncogenic transformation of the cells." (PMID 30011933, 2018). "GGCT (gamma‐glutamylcyclotransferase), a key enzyme in the gamma‐glutamyl cycle, is significant in cancer metabolism and therapy resistance." (PMID 39641316, 2024). "The data obtained revealed that with the exclusion of PTP4A3 and GGCT, and the levels of TTEP expressions were significantly (p < 0.05) associated with the resistance of cancer cell lines to several classes of small molecules of anti-cancer functions." (PMID 35990603, 2022). "GGCT has been reported to be upregulated in several cancers, and depletion of GGCT can exert anticancer effects in these cancers, including prostate, esophageal squamous cell carcinoma, breast, gastric, and ovarian cancers." (PMID 36233293, 2022). "Another important player in cancer cell proliferation has been demonstrated to be the glutamylcyclotransferase enzyme (GGCT)." (PMID 34943605, 2021). "GGCT genomic locus amplification can directly lead to GGCT mRNA up-regulation, suggesting a cancer-driving function of GGCT in human cancer." (PMID 31400748, 2019). "We checked GGCT mRNA expression in various human cancers and indeed found that the mRNA of GGCT was up-regulated in various cancers compared with each control tissue, and in several cancer types this difference reached statistical significance." (PMID 31400748, 2019). "It is already known that protein and mRNA expression of GGCT is up-regulated in multiple types of cancers." (PMID 31400748, 2019). "To further validate the induction of GGCT by Ras signaling, we knocked down KRAS gene in human cancer cells and observed that GGCT transcription is down-regulated." (PMID 31400748, 2019). "In summary, our comprehensive cancer genomic and mouse model studies indicate that both oncogenic signal (Ras activation) and chromosomal 7p amplification lead to GGCT expression up-regulation in human cancers." (PMID 31400748, 2019). "In early-stage cancer, GGCT up-regulation makes a difference in patient prognosis, meaning a specific function of GGCT in early-stage cancer, probably in cancer initiation." (PMID 31400748, 2019). "In summary, here we provide human cancer genomic evidence supporting the oncogenic function of GGCT." (PMID 31400748, 2019). "It is known that GGCT mRNA and protein expression are frequently up-regulated in cancers compared with normal control tissues." (PMID 31400748, 2019). "Subsequent studies indicated that GGCT protein or mRNA is overexpressed in multiple human cancers including breast, lung, esophagus, stomach, bile duct, and uterine cervix cancer." (PMID 31400748, 2019). "Here we identified a novel oncogenic Ras downstream target GGCT, and further characterized GGCT function using mouse models, cancer genomics, and cell biochemical approaches." (PMID 31400748, 2019). "Based on these observations, GGCT is now recognized as a promising therapeutic target in various cancers." (PMID 30011933, 2018). "Accordingly, many studies have recently described high expression levels of GGCT/C7orf24 in various cancers." (PMID 30011933, 2018). "Taken together, the data of these studies using clinical samples show that GGCT upregulation is a common event in a wide range of malignant tumors." (PMID 30011933, 2018). "The upregulation of GGCT has been reported in a wide range of cancer cell lines including breast, ovarian, cervical, lung, urinary bladder, prostate, colon cancers, osteosarcoma, and glioma cells." (PMID 30011933, 2018).